BMP1 (bone morphogenetic protein 1)
Diseases named in the same sentence as BMP1 in open-access papers (continued):
Sharing a sentence is not in itself a finding about the gene and the disease.
tumor (continued). "Thus, BMP1 in PANC1 cells caused increased collagen deposition and reduced tumor growth and metastasis to a greater extent than was observed with BxPC3 cells." (PMID 33879793, 2021). "Here, we revealed the underlying mechanism of IL-1β-promoted tumor cell stemness by studying BMP1/5/8 and ID1 signaling pathway, but not TGF-β/Smad2/3 signaling pathway." (PMID 32547321, 2020). "We found that BMP1 knockdown in Caki-1 cells significantly reduced tumor volume and tumor weight." (PMID 31155610, 2020). "BMP-1 overexpression in ECs was shown to be restricted to areas of tumor angiogenesis in vivo." (PMID 29541388, 2018). "Hence, we here hypothesize that a marked secretion of BMP-1 by metastatic cells enhances tumor growth and alters drug response." (PMID 39792296, 2025). "Although BMP-1-mediated activation of TGF-β signaling might play an important role in tumor-promoting effects of BMP-1 and consequently, BMP-1 inhibitors should have anti-tumoral effects, our results demonstrate that mechanisms other than TGF-β activation are also involved." (PMID 39792296, 2025). "In addition, our results suggest that BMP1 might exert its oncogenic roles by increasing tumor immune cell infiltration and immune checkpoint expression." (PMID 37848987, 2023). "It is demonstrated that bone morphogenetic protein 1 (BMP1) overexpression is common in GC, and when suppressed, it inhibits tumor cell motility." (PMID 41451347, 2025). "In turn, BMP1 activates latent TGF β-binding proteins and remodelling ECM proteins, to augment the invasive capabilities of tumor cells and modulate signalling by TGF beta families." (PMID 41348904, 2025). "In comparison to non-tumor samples, it was observed that the protein levels of TGFβ-1, IL19, CXCR4, BMP1, VCAN, and WNT2 were significantly enhanced in several tumor samples." (PMID 41348904, 2025). "This core network of IL-19, TGFβ-1, CXCR4, BMP1, VCAN, and WNT2 reveals a tight-knit module that regulates tumor aggressiveness, immune evasion, and therapy resistance." (PMID 41348904, 2025). "X Wu reported that downregulation of BMP1 leads to suppression of TGFβ and matrix metalloproteinases 2 (MMP2) and MMP9, and finally decreased tumor invasion in NSCLC." (PMID 39963673, 2025). "Meanwhile, bone morphogenetic protein 1 (BMP1) and ANGPT2, which respectively facilitate tumor growth and angiogenesis, were expressed at significantly higher levels in SMC_1." (PMID 35999201, 2022). "Immunohistochemical staining was performed to visualise the expression of BMP1, CD109, LTBP1, PSAP, and NPC2 in human control colonic tissue, primary tumour, and liver metastasis." (PMID 36134447, 2022). "This led to the further discovery that BMP1 and its cancer-cell-derived fibrillar procollagen substrates both act as suppressors of PDAC tumor growth and metastasis." (PMID 33879793, 2021). "Both the PCOLCE and mut COL1A1 experiments supported the notion that BMP1, with help from PCOLCE, cleaves procollagen I to stimulate its deposition, which leads to suppression of tumor growth and metastasis." (PMID 33879793, 2021). "The mRNA levels of TEK, BMP1, AR, SLC11A1, SLC40A1, and F2RL1 were significantly downregulated in tumor cells compared with normal cells, and CX3CL1 and RNASE2 were upregulated in tumor cells." (PMID 35004689, 2021). "IHC results validated that the protein expression of FAP, BMP1, WNT5A were upregulated in tumor." (PMID 35999201, 2022). "Cleavage by the BMP-1 protease also released the catalytically inactive N-terminal LOX-PP peptide, which functions as an inhibitor of the ras signal transduction pathway and as a tumor suppressor." (PMID 36232621, 2022). "BMP1, CD109, and LTBP1 showed a gradual and clear increase of expression from the control tissues to the metastatic tissues, with preferential cytoplasmic staining in the tumour tissue, being more intense in metastasis." (PMID 36134447, 2022).
tumor (continued). "Here, the authors show that fibrillar collagen that is cancer-cell-derived, but not stroma-derived, selectively restrains tumor growth under control of their pC-proteinase, BMP1." (PMID 33879793, 2021). "For example, four growth factors (TGFB1, HGF, BMP1 and PDGFB) that are well-known to induce EMT, exhibited higher expression levels in CD4/8+ T cells compared with other immune and tumor cells, suggesting that anti-immune evasion promotes EMT as well by producing growth factors which induce EMT." (PMID 34158591, 2021). "Among them, PANC1 cells had the highest COL1A1 expression and the largest tumor-suppressing effect by BMP1, while AsPC1 had the lowest COL1A1 expression and no BMP1 effect (see the next section for COL1A1 expression data)." (PMID 33879793, 2021). "Similarly, the Wnt pathway has been shown to drive Tgfb1 and Bmp1 signaling and the promotion of a collagen-rich fibrotic phenotype that excludes T cell infiltration of the tumor." (PMID 36537914, 2022). "Among them, we mainly analyzed four genes (EGFR and BMP1 in ESCC and IL-1B and MAPT in EAC) that were related to gender, tumor stage, lymph node metastasis, distant metastasis, and other clinical features in EC, supposing that they might play essential roles in the prognosis of EC patients." (PMID 33859939, 2021). "Alternatively, increases in BMP1 may have tumour suppressive effects in Ras transformed cancers, where post-translational processing in cells highly expressing LOX and LOXL1 would increase levels of the tumour suppressive LOX pro-peptide." (PMID 33513979, 2021). "It will be interesting to see whether various possible means to increase the extracellular content of pro-LOX, e.g. by inhibiting the cleavage of pro-LOX with BMP1 inhibitors or with competitive pro-LOX-specific cleavage site peptides, would offer a viable strategy to inhibit tumor progression." (PMID 30701028, 2018).
cancer (33 papers, 2010 to 2025). A tumor composed of atypical neoplastic, often pleomorphic cells that invade other tissues. "Among BMP-1 substrates several of them are associated with the progression and metastasis of cancer." (PMID 39792296, 2025). "LOX, activated by BMP-1, causes stiffening of the matrix and enhances the invasive and metastatic properties of cancer cells." (PMID 39792296, 2025). "The presence of cancer and control-associated isoforms suggests differential regulation of BMP1 isoforms." (PMID 36989217, 2023). "In recent years, it was found that BMP1 is highly expressed in some cancers and associated with cancer invasiveness in gastric cancer, lung cancer, osteosarcoma, colon cancer and renal cancer." (PMID 37848987, 2023). "Our results suggest that association of BMP-1 with high grade tumors and poor prognosis might be due to increased survival of cancer cells and resistance to chemotherapy." (PMID 39792296, 2025). "Our study determined that BMP1 expression in pancancer is associated with poor prognosis and highlights that BMP1 may be a potential clinical and therapeutic predictor in various cancers." (PMID 36267461, 2022). "It pointed out that there may be an underlying correlation between the m6A modification and BMP1 expression in various cancers, particularly impacting the pullulation and prognosis of those cancers through regulating IGFBP3." (PMID 36267461, 2022). "BMP-1 is an ECM protein associated with high-grade tumors and/or poor prognosis in several types of cancers." (PMID 39792296, 2025). "DKK3 and BMP1 treatment in cancer cells; dormancy confirmed by live-cell imaging and co-staining for Ki-67-/p27+; p-p38 nuclear translocation assessed by IF." (PMID 41404065, 2025). "Inhibition of BMP-1 activity markedly suppressed proliferation of cancer cells and enhanced anti-tumoral effects of doxorubicin." (PMID 39792296, 2025). "We did not observe anti-proliferative effects of UK in MCF-7 cells after acute as well as extended periods of treatments suggesting that BMP-1 plays a cancer promoting role in aggressive cells that have metastatic potential." (PMID 39792296, 2025). "BMP-1 is also one of the ECM proteins associated with high-grade tumors and/or poor prognosis in several types of cancers." (PMID 39792296, 2025). "We used the TCGA and GEPIA databases to analyze relative expression of BMP1 in various types of human cancer." (PMID 37848987, 2023). "In general, we demonstrate that BMP1 is highly expressed in multiple types of human cancer (including ccRCC) and strongly correlates with unfavorable prognosis in ccRCC." (PMID 37848987, 2023). "To address these questions, we first investigated expression of BMP1 and its prognostic significance in a variety of human cancers." (PMID 37848987, 2023). "We first investigated expression of BMP1 across cancers using TCGA data, after which the GEPIA database was also used to confirm BMP1 expression." (PMID 37848987, 2023). "We first detected expression of BMP1 in 18 types of human cancer to illuminate the roles of BMP1 in carcinogenesis using the TCGA database." (PMID 37848987, 2023). "Survival analysis for BMP1 in cancer types of interest indicated that ccRCC patients with high expression of BMP1 had poor prognosis." (PMID 37848987, 2023). "Gene Set Cancer Analysis analyzed the correlation of BMP1 expression level with copy number variations and methylation." (PMID 36267461, 2022). "Five genes, AXIN2, BMP1, CR1, ERBB2, and RYR1, have been recorded of association with birth defects and cancer." (PMID 36384586, 2022). "This research explores the underlying link between diagnosis and therapy between bone morphogenetic protein 1 (BMP1) and various cancers." (PMID 36267461, 2022). "Except for a few cancer types, methylation negatively correlated with BMP1, and copy number variations positively correlated with BMP1." (PMID 36267461, 2022).
cancer (continued). "The findings in this article highlight the immunological effect of BMP1 in fractional carcinomas, but further research is required." (PMID 36267461, 2022). "There has been little research thus far examining the use of BMP1 inhibitors in combination with chemotherapeutics to specifically treat LOX/LOXL1 overexpressing cancers." (PMID 33513979, 2021). "IHC experiments showed that oe-BMP1 in cancer cells induced higher ColI protein deposition by both cancer cells and stromal cells in the xenograft tumors." (PMID 33879793, 2021). "Lenti-BMP1 PANC1 orthotopic xenograft tumors had a markedly increased ColI deposition in both cancer-cell and stromal-cell compartments by IHC, by WB analysis of enriched ECM, and by Hypro measurement of overall collagen level." (PMID 33879793, 2021). "WB analysis on the enriched insoluble ECM showed that ECM from oe-BMP1 tumors contained a higher deposition of cancer-cell-derived ColI, while the fractions of the stromal- and cancer cell/stroma-derived ColI were only marginally increased." (PMID 33879793, 2021). "For survival analysis, cancer patients that just enrolled into the study was excluded, and the remaining patients were divided into two groups according to the status of BMP1 expression." (PMID 29720137, 2018). "Our data suggested the BMP1 likely promotes cancer cell migration through both faster extracellular matrix remodeling and activation of the TGF-β signaling." (PMID 29720137, 2018). "The first group comprised patients with a BMP1 expression level above the median for all cancer specimens, while the other group had below-median levels of BMP1 expression." (PMID 29720137, 2018). "Among miR-204 gene targets that are potential regulators of cell-matrix interaction and proteolysis, overexpression of APRC1B, CTSC, FAP, MMPs, BMP1, CDH11 and ITGB4 is associated with cancer metastasis and/or poor prognosis." (PMID 20369013, 2010). "The opposite pattern of abundance of the long and short isoforms in early NSCLC subjects versus healthy subjects suggest that BMP1 isoforms may play a role in cancer and may serve as a novel biomarker." (PMID 36989217, 2023). "Then, we further examined BMP1 expression in these 18 cancer types through the GEPIA database." (PMID 37848987, 2023). "GEPIA was used to perform survival analysis for BMP1 in various cancer types." (PMID 37848987, 2023). "BMP1 is a potential biomarker and mediator in diversified malignant tumors, whereas the function and pathway of its impact on pancancer remain unclear." (PMID 36267461, 2022). "The BMP1 expression landscape of 33 cancer types was presented in our study." (PMID 36267461, 2022). "However, there had inconsistency between BMP1 activity and expression in some types of cancers (DLBC and GBM)." (PMID 36267461, 2022). "Moreover, the activity of BMP1 was notably decreased in the cancer groups of BLCA, BRCA, CESC, KICH, PRAD, and UCEC." (PMID 36267461, 2022). "A recent study implicated the upregulation of EMT transcription factors (BMP1, CDH2, KRT14, etc.)to high proliferation rates, mechanical molecular barriers disassembly, and increased cancer cell motility, leading to metastasis risk in pulmonary neuroendocrine neoplasms." (PMID 36267461, 2022). "BMP1 may serve as a potential biomarker for prognostic prediction and immunologic infiltration in diversified cancers, providing a new thought approach for oncotherapy." (PMID 36267461, 2022). "For example, although BMP1 is usually upregulated with collagens in cancers, including PDAC11,35,36, the upregulation of BMP1 expression may not be sufficient to effectively cleave the greatly elevated levels of fibrillar collagens." (PMID 33879793, 2021). "Whether the different roles of BMP1 in other cancers relate to the amount of collagen produced will be an interesting question for future studies." (PMID 33879793, 2021).
cancer (continued). "Unlike control cells, cancer cells knocked down for COL1A1 no longer respond to the increase in stromal-cell-derived collagen caused by lenti-BMP1." (PMID 33879793, 2021). "Analyses of BMP1 functions in cancer are somewhat limited and conflicting." (PMID 33879793, 2021). "Effectively, this study showed that LOX activity and subsequent collagen cross-linking within the ECM could be altered through cancer induced changes to BMP1 production." (PMID 33513979, 2021). "UK383367 resulted in an increased amount of C-pro/α1(I) on collagen fibers by immunostaining and Western blotting (WB) from cultured CAFs and decreased total collagen I deposition by WB in a dose-dependent manner in cultured CAFs and cancer cells, confirming that it is an inhibitor of BMP1." (PMID 33879793, 2021). "The BMP1 substrate LTBP1 was expressed at similar levels in all but only one cancer patient." (PMID 29720137, 2018). "Furthermore, it has been demonstrated that the propeptide of LOX (ppLOX), which is the liberated form of the LOX precursor by cleavage with protease bone morphogenetic protein 1 (BMP1), inhibits cancer-associated DNA repair." (PMID 25978957, 2015). "BMP1 plays a role in collagen processing and the short isoform lacks the domains enabling its secretion, potentially impacting collagen’s protective role in cancer consistent with the higher abundance of the short isoform in cancer subjects observed in this paper." (PMID 36989217, 2023). "Furthermore, these cancers had an inverse effect on BMP1 expression." (PMID 36267461, 2022). "Likewise, BMP1 expression had inversely affected these cancers." (PMID 36267461, 2022). "Furthermore, low methylation meant high BMP1 expression in some cancers (LUSC, PRAD, and LIHC)." (PMID 36267461, 2022). "Maximum of the cancers displayed the pattern, with enhanced expression of IL19, TGFβ-1, CXCR4, BMP1, VCAN, and WNT2 protein levels in the samples of KICH, KIRC, LUAD, LUSC especially BRCA when compared to normal samples." (PMID 41348904, 2025). "For DFS, increased expression of BMP1 indicated unfavorable prognosis in KIRC (log-rank p = 0.0041, HR = 1.7, p = 0.0046) among all cancer types." (PMID 37848987, 2023). "The relationships between mRNA expression of BMP1 and CNV and methylation in various cancer types were explored based on the GSCA platform." (PMID 36267461, 2022). "Currently, anti-BMP1 inhibitors are available, and STAT3 and TGF-β inhibitors are being tested for their efficacy against a variety of cancers in clinical trials." (PMID 29720137, 2018). "BMP1 was not statistically significant in predicting the prognosis of patients with other types of cancer." (PMID 37848987, 2023). "Additionally, we explored BMP1 expression in CNV and the methylation profile of human cancers to focus on the activity of regulatory factors and regulation of intracellular signaling, which is also considered momentous." (PMID 36267461, 2022). "In some cancers (LUSC, PRAD, LIHC, and OV), a higher CNV meant a higher BMP1 expression." (PMID 36267461, 2022). "BTP family members in humans include bone morphogenetic protein-1 (BMP-1), mammalian Tolloid (mTLD), and mammalian Tolloid-like-1 (mTLL-1) and -2 (mTLL-2).They have been shown to control many aspects of development, growth and tissue repair, and are involved in diseases such as cancer and fibrosis." (PMID 29209066, 2017). "Quantification of cancer-cell-derived ColI level by IHC showed that WT, but not mut, PCOLCE further promoted ColI deposition in oe-BMP1 tumors." (PMID 33879793, 2021).
infection (10 papers, 2009 to 2026). The state of being infected such as from the introduction of a foreign agent such as serum, vaccine, antigenic substance or organism. "In B. cinerea, the deletion of BMP1, Ste7, Ste11, or Ste50 causes defects in the development of infection-related structures, confirming that BMP1 MAPK signaling is likely regulated by the surface sensor Msb2." (PMID 35634482, 2022). "Bcgbl1 mutants had reduced phosphorylation levels of two MAPKs, namely Bmp1 and Bmp3, thereby reducing infection." (PMID 38048363, 2023).
autosomal recessive disease (1 paper, 2020). Autosomal recessive form of disease. "Loss-of-function mutations in BMP1 result in abnormal collagen formation and occur in various autosomal recessive diseases associated with defective osteogenesis." (PMID 32953253, 2020).
cardiovascular diseases (1 paper, 2022). "Members of transforming growth factor-β superfamily, which include the largest members of bone morphogenetic proteins (BMP1–9), are implicated in aging, cardiovascular diseases, AD and VCID." (PMID 35948662, 2022).
BMP1 also shares sentences with these, for which no sentence is quoted: non-small cell lung carcinoma (4 papers); osteosarcoma (3); liver (2); anaplastic thyroid carcinoma (1); bacterial infections (1); Bruck syndrome (1); carcinoid tumor (1); cardiac sarcomas (1); Cardiomyopathies (1); central precocious puberty (1); cervical cancer (1); Cirrhosis (1); corneal dystrophies (1); endothelial dysfunction (1); esophageal squamous cell carcinoma (1); fibrosis (1); gastritis (1); gastroenteritis (1); gastroschisis (1); hepatocellular carcinoma (1); hypercholesterolemia (1); hyperprolactinemia (1); Hypertension (1); hypertrophy (1); idiopathic pulmonary fibrosis (1); ischemic stroke (1); kidney infection (1); lymphoma (1); Metabolic Disorders (1); metastatic cancer (1).
A further 17 diseases each share a sentence with BMP1 in 1 paper.